CRP (C-reactive protein)
Diseases named in the same sentence as CRP in open-access papers (continued):
Sharing a sentence is not in itself a finding about the gene and the disease.
tumor (continued). "We observed that patients with sCRS had significant differences in the initial tumor load, platelets, neutrophil count, lymphocyte percentage, white blood cells, monocyte count, CRP, dosage, IL-2, D-dimer, TAG, red blood cells, hemoglobin, and procalcitonin, as compared with patients without sCRS." (PMID 37854590, 2023). "The finding by Ronning and authors of elevated pre-treatment CRP in frail groups may correlate with tumor-mediated inflammatory response." (PMID 37213604, 2023). "CRP could be a biomarker of inflammation in the tumor microenvironment (TME), and chronic inflammation plays an active role in cell proliferation and tumorigenesis." (PMID 38071306, 2023). "This might be explained by the possibility that tumor cells release cytokines that induce CRP elevation or that CRP elevation is a substituted marker for the active release of cytokines that promote tumor cell proliferation." (PMID 36875097, 2023). "The upregulated proteins, including MMP9 (matrix metalloproteinase-9), ADAMTS13 (ADAM metallopeptidase with thrombospondin type 1 motif 13) and CRP (C-Reactive Protein), are known to be involved in extracellular matrix remodeling, vascular permeability and tumor-promoting inflammation." (PMID 36831450, 2023). "CRP-MC (Trip) had a tumor-suppressing effect similar to that of the gemcitabine." (PMID 36869341, 2023). "Both elevated preoperative AFP and CRP levels are linked to larger tumor diameter, a higher incidence of multifocal disease, microvascular invasion, and more advanced BCLC staging—all of which are recognized indicators of tumor aggressiveness (all P < 0.05)." (PMID 38053048, 2023). "Similarly, the intrahepatic tumor number, macrovascular invasion, BCLC stage, NLR, and CRP level were identified as significant predictors associated with the PFS based on RECIST v1.1." (PMID 36749777, 2023). "Interestingly, in this study, the first 68Ga-DOTATATE PET/CT was performed early (after two cycles of treatment); at this time point, CRP and neutrophil-to-lymphocyte ratio were predictors of change in tumor burden." (PMID 35450421, 2022). "C-reactive protein elevation is believed to reduce T-lymphocyte response to tumor, which may contribute to disease progression." (PMID 36718344, 2022). "Elevated serum CRP level may be a sign of a high tumor burden or catabolic effects on the metabolism." (PMID 35575465, 2022). "The absence of tumour-associated MMP-8-positive PMNs together with an elevated CRP level associated with an unfavourable prognosis (HR = 2.99; 95% CI 1.60–5.59; p = 0.001) compared to a positive PMN score and a low CRP level." (PMID 35328734, 2022). "Our results showed that patients with CRP/ALB > 1.9 before tumor removal had shorter PFS and OS." (PMID 35873678, 2022). "In comparison with the control group, the observation group exhibited a lowered ADPN level (p<0.05), notably raised levels of plasma D-D, inflammatory factors hs-CRP and interleukin-6 (IL-6) and serum tumour markers CA125 and HE4 and an evidently increased ROMA (p<0.05)." (PMID 35431651, 2022). "In the training cohort, a significant association between shorter OS and high NMPR (p = 0.04) as well as high CRP (p < 0.001), poor tumor differentiation (p = 0.008), advanced T stage (p = 0.006), advanced N stage (p < 0.001) and high CEA (p = 0.007) was revealed." (PMID 36557010, 2022). "Moreover, CRP can enhance cytotoxic T lymphocyte-mediated cell lysis and, on the other hand, can promote a sustained pro-inflammatory and pro-tumor immune microenvironment." (PMID 36612251, 2022). "Plasma CRP has been proposed as a sensitive serological surrogate parameter for elevated levels of proinflammatory cytokines stimulating angiogenesis, tumor proliferation, and growth, being an easily measurable biomarker, which is routinely analyzed before treatment initiation." (PMID 35158759, 2022).
tumor (continued). "In patients with advanced tumors, some inflammatory factors such as tumor necrosis factor alfa, interleukin 6, and interleukin 1 beta can induce the synthesis of CRP in hepatocytes while promoting angiogenesis to support tumor growth and anti-apoptosis capabilities to protect tumor cells." (PMID 36266627, 2022). "Emerging evidence showed that CRP may also participate in tumor progression and metastasis in patients with HCC." (PMID 35756674, 2022). "However, the change in CRP concentration should only be an ancillary tool to predict the outcome, the response to treatment and the invasiveness of the tumor as well as to monitor over time the response to treatments and it cannot replace diagnostic imaging." (PMID 36290272, 2022). "Serum CRP reflects systemic inflammatory response and, if combined with other markers of the systemic inflammatory response, it is a useful prognostic biomarker for several tumor types." (PMID 36612251, 2022). "However, the single level of ALB is often of little significance in clinical application, and the ratio of CRP to ALB was always be used to evaluate the disease status of tumor patients." (PMID 35280511, 2022). "Although the underlying mechanism of CRP correlation with poor prognosis is not fully elucidated, studies suggest that elevated CRP is associated with infiltration of immune suppressor cells including regulatory T cells and tumor-associated macrophages." (PMID 35978814, 2022). "MMPs are known mediators of inflammatory processes at the tumour site which may eventually lead to systemic inflammation and CRP elevation." (PMID 35328734, 2022). "However, an extensive research paper published in 2020 shows that CRP concentrations in patients with immune-mediated and neoplastic diseases rise most frequently of all and to the greatest extent." (PMID 36290272, 2022). "Our findings indicated that the maximal tumor dimension was significantly associated with the protein inflammatory markers, i.e., CRP and AGR, but not with cellular-based indicators." (PMID 35629255, 2022). "Moreover, future trials have to elucidate if those patients having increased serum CRP levels will benefit from early stereotactic radiosurgery in case of residual or progressive tumor." (PMID 34882287, 2022). "Moreover, a positive correlation of HMGB1 levels with tumor volumes, C‐reactive protein (CRP) levels, infections, and grade three toxicity (RTOG) was observed." (PMID 34671818, 2022). "Pretreatment CRP may also help, along with other markers in a model, to guide clinical decision-making for ICIs, as it is likely to reflect the biology of the tumor and/or its microenvironment." (PMID 34757531, 2022). "The results showed that Age (p < 0.001), Sex (p = 0.0041), Hemoglobin (p < 0.001), ASA score (p = 0.048), C-reactive protein (p = 0.001), ECOG score (p = 0.005), NRS2002 (p < 0.001), LCR (p < 0.001), and Tumor location (p = 0.003) were associated with the occurrence of anastomotic leakage." (PMID 35870933, 2022). "The tumor microenvironment can trigger the release of key proinflammatory mediators including interleukin-6 (IL-6), IL-1, and IL-1β, which stimulate hepatocyte CRP production, leading to a marked increase in plasma CRP." (PMID 35978814, 2022). "In the present study, CRP and NLR, which might be affected in the tumor microenvironment by immune cells, were associated with worse OS." (PMID 34757531, 2022). "Additionally, IL-6, a chronic inflammatory protein that induces CRP expression, was also reported to have a potential immune suppressive function and promote tumor progression by inducing tumor cell expression of STAT3 and its downstream target genes." (PMID 35185894, 2022). "CRP was associated with stage, but not tumor grade, LVSI or age at diagnosis, and the study failed to control for other important prognostic parameters, for example BMI, T2DM and depth of myometrial invasion." (PMID 34802721, 2022).
tumor (continued). "These and other biological features make CRP an attractive potential tumor marker." (PMID 35461024, 2022). "The associations observed for CRP genetic variation did not change substantially after stratification by sex, tumor location or tumor stage." (PMID 35739525, 2022). "Tumor size and CRP level were also prognostic factors in multivariate analysis." (PMID 36358634, 2022). "As the tumor grows, the level of CRP continues to rise; this is in line with previous studies." (PMID 36359174, 2022). "Coincidingly, it is hypothesized that elevated CRP may be associated with a downregulation of the antitumor immune responses of ICIs due to its correlation with immunophenotypes of ICI resistance, tumor growth, and poor prognosis." (PMID 35978814, 2022). "Patients with larger tumours more often had higher CRP than patients with less extensive tumours." (PMID 33740951, 2021). "Likewise, the univariate analysis indicated that CRP, Child–Pugh grade, vascular invasion, tumor stage, degree of differentiation, PNI, and NLR were significant predictors of RFS (p < 0.001)." (PMID 35155212, 2021). "Similarly, markers of inflammation, such as CRP, albumin or leucocyte-based ratios, were shown to predict tumor progression in a variety of solid tumors." (PMID 34148164, 2021). "We hypothesized that CRP might serve as an additional component for immunonutritive scoring because it could reflect the inflammatory component of the tumor microenvironment." (PMID 34638502, 2021). "Protein was administered by intravenous injection of 100-200 μl test agent (containing ~ 100 μg CRP protein) every second day for 14 days, beginning on the first day actual tumor could be palpated on the flank of the mouse (day 7)." (PMID 34552600, 2021). "CRP is an acute-phase reaction protein, and its production is stimulated by interleukin-6, a cytokine released during the systemic inflammatory response to the tumor." (PMID 34944774, 2021). "We therefore propose a model in which tumor diseases to a variable extent (reflected by neutrophils and CRP) may induce a “pre‐inflammatory” state in the patients, that predisposes them to a hyperinflammatory reaction when they are infected with the virus." (PMID 34121360, 2021). "Serum CRP levels were correlated with liver functions and tumor stages in patients with HCC." (PMID 35070979, 2021). "In addition, CRP (52.9 mg/L) and CEA (1.810 ng/mL) concentrations were the highest in stage IV of GC; however, the statistically significant differences between tumor stages were found only for CRP concentrations (p = 0.044)." (PMID 34680333, 2021). "In univariable analysis, NLR, PLR, hemoglobin, AGR, tumor size, CRP, mGPS, R.E.N.A.L." (PMID 34136403, 2021). "Baseline CRP and tumor response were prognostic of overall survival." (PMID 34900709, 2021). "Moreover, serum levels of CXCL8, CXCR2 and classical tumor markers were higher in Lauren type 2 than in patients with Lauren type 1, while CRP concentrations were the highest in patients with Lauren type 1." (PMID 34680333, 2021). "This evidence prompted us to hypothesize that the level of serum CRP might correlate with the immune context at the tumor site of HCC patients." (PMID 35070979, 2021). "However, significant differences were not seen in demographic figures (age and gender), clinical features (patterns of edema and weight loss), and laboratory features (CRP, ESR, immunoglobulin, complement, and tumor markers)." (PMID 34654466, 2021). "CRP level (p=0.016) and tumor response (p=0.021) were independently prognostic of OS." (PMID 34900709, 2021). "Elevated serum inflammatory biomarkers including C-reactive protein (CRP), IL-6, and serum amyloid A (SAA) were positively associated with an increased risk of recurrence of HR+/HER2- tumor, and higher CRP level was correlated with detectable serum estrogen metabolites." (PMID 35008370, 2021).
tumor (continued). "In a retrospective, multi-institutional study of 7,426 patients who underwent RP, pre-prostatectomy CRP levels were associated with pathologic Gleason score, but not tumor stage." (PMID 34512646, 2021). "Interestingly, CA19-9 is a typical PDAC biomarker whereas CRP is thought to reflect the patient’s systemic reaction to the tumor." (PMID 33437015, 2021). "In addition, CRP should also be further evaluated as a potential therapeutic adjuvant for tumor eradication." (PMID 33790888, 2021). "Due to the tumor-promoting roles of TAMs and TANs, these results might partially explain why serum CRP is an indicator of a progressive tumor." (PMID 35070979, 2021). "The adverse association of CRP/MCV with overall survival seems to be stronger among women, poor differentiation, early T stage, advanced N stage, advanced TNM stage, and right-side tumor patients." (PMID 34221966, 2021). "After correction for our MV- inflammation model (age, gender, BMI, smoking, TCL, plasma glucose, SBP, prevalent CVD and CRP), two tumour biomarkers CA15-3 and CEA (HR 2.88, 95% CI 1.58–5.24 and HR 1.87, 95% CI 1.33–2.64) remained strongly associated with CV mortality." (PMID 34957244, 2021). "CRP elevation is an independent predictor for survival, as well as tumor recurrence." (PMID 34512646, 2021). "Accumulating evidence indicated the role of CRP in the tumor development and metastasis." (PMID 34221991, 2021). "Active brain metastases, a higher number of metastatic sites, lower albumin and absolute lymphocyte count (ALC), higher C-reactive protein (CRP) and neutrophil-to-lymphocyte ratio, higher total metabolic tumor volume (TMTV), and higher ctDNA levels were associated with worse survival." (PMID 33418936, 2021). "CRP has recently been shown to have important predictive value in tumor immunotherapy." (PMID 34859069, 2021). "This suggests the possibility that CXCR4 could become a prognostic factor in a combined analysis with classical tumor markers such as carcinoembryonic antigen and C-reactive protein levels." (PMID 33579381, 2021). "If confirmed, the combination of neutrophil count and serum CRP (determined at any given time point prior to SARS‐CoV‐2 infection), could be employed as an easy‐to‐obtain biomarker to identify tumor patients at particular risk for a severe course of COVID‐19." (PMID 34121360, 2021). "In univariate analyses, serum albumin was also a predictive factor; additionally, we consider that the immunosuppressive tumor microenvironment (indicated by a higher serum CRP) may play a critical role in nivolumab treatment." (PMID 33635904, 2021). "In addition, CRP has prognostic value in various malignancies and can be used to predict treatment response and tumour recurrence." (PMID 33514832, 2021). "However, chronic inflammation results in tumour angiogenesis and DNA damage, which both increase C-reactive protein (CRP) levels." (PMID 33740951, 2021). "On the other hand, high CRP was related to sustained inflammation, which may reflect a pro-angiogenic tumor microenvironment, as high CRP upregulated the expression of VEGF permitting tumor proliferation and metastasis." (PMID 34778081, 2021). "Different serum CRP levels may serve as a basis for prognostic stratification, especially in moderately differentiated (G2) tumours." (PMID 34887479, 2021). "This study showed that although tumor-associated CD66b(+) neutrophils and CD163(+) macrophages were correlated with adverse prognostic factors in NSCLC—such as a higher CRP, a higher white blood cell count, larger tumor size, and necrosis—no direct link to the patients’ outcome was observed." (PMID 34885082, 2021). "As a predictive marker, C-reactive protein (CRP) may be of value as its concentration increases with tumor size and regional metastasis, especially in NSCLC." (PMID 34690552, 2021).
tumor (continued). "It has been reported that tumor and stromal cells, including TAMs and TANs, secreting inflammatory IL-1 and IL-6 could be responsible for the elevated synthesis and secretion of CRP by hepatocytes." (PMID 35070979, 2021). "This study, for the first time, demonstrates that preoperative serum CRP is an independent risk factor for postresection survival regardless of tumour differentiation and tumour advancement." (PMID 34887479, 2021). "In this setting, elevated preoperative CRP is associated with higher tumor stage, but was not independently correlated with disease recurrence." (PMID 34512646, 2021). "Similarly, CRP levels have correlated with tumor burden, indicating the aggressiveness of advanced pancreatic cancer." (PMID 33437015, 2021). "These markers (CRP and albumin) have been examined for creating risk groups of patients with DLBCL28, and the prognostic value of the CAR has also be considered based on the changing CRP and albumin levels in the tumour microenvironment." (PMID 33514832, 2021). "Indeed, C-reactive protein levels closely correlate with the tumor-induced immunosuppression in mRCC." (PMID 33572149, 2021). "Elevated CRP levels are thought to reflect host reactions to the biological behavior of a tumor." (PMID 34221966, 2021). "Thus, in an MR framework, the elevated CRP concentrations are less likely to result from the immune response induced by premalignant or preclinical tumor growth." (PMID 33614510, 2020). "Serum CRP levels were also correlated with tumor size and stage of EOC." (PMID 33208875, 2020). "C-reactive protein (CRP) has been assessed as a marker of outcome in a plethora of tumor entities." (PMID 32423000, 2020). "Yet to be explored is whether CRP within the tumor microenvironment impedes the anti-tumor response directly (i.e. by inhibiting T cells per se) or indirectly (i.e. by promoting MDSCs)." (PMID 33633738, 2020). "For the first time we demonstrated a significant interaction of circulating CRP with tumour cell specific PD-L1 expression indicating that the prognostic value of PD-L1 might be influenced by CRP." (PMID 32238865, 2020). "PNI and GPS consist of albumin and lymphocytes or C-reactive protein (CRP), which may reflect the balance between the pro-tumor inflammatory status and nutritional status." (PMID 33129309, 2020). "First, tumor growth induces tissue inflammation and increases CRP level." (PMID 33351844, 2020). "Moreover, a pathologically enhanced CRP level was found to be connected with tumorous vascular invasion corresponding to greater tumor burden and subsequent increased tumor stage (p = 0.017)." (PMID 31936329, 2020). "Increased CRP levels may indicate a more aggressive tumor and pronounced inflammation inside the tumor microenvironment." (PMID 32604773, 2020). "Similarly, the results of our study revealed a significant relationship between an increase in plasma CRP and advanced tumor stage." (PMID 32182693, 2020). "A previous study demonstrated that CRP is positively correlated with the pathological tumor size and pathological stage in NSCLC patients; thus, the preCRP level might be a prognostic indicator for NSCLC patients who have undergone surgery." (PMID 33059654, 2020). "The complex of CRP-SAA could increase the CXCL cytokines and angiopoietin-like proteins in the synergistic way, so we hypothesized the CRP-SAA participated in a wide range of processes that contributed to tumor development and progression." (PMID 33364190, 2020). "Combining CRP and tumor stage enhanced the predictive power of CRP." (PMID 33201589, 2020). "In addition, elevated CRP accelerates angiogenesis based on increased vascular growth factors and interleukin, and leads to tumor progression." (PMID 32441463, 2020). "The purpose of this study was to evaluate the diagnostic capability of CRP in EOC, and whether it can be combined with tumor markers to enhance EOC diagnosis." (PMID 33208875, 2020).